TNF (tumor necrosis factor)
Diseases named in the same sentence as TNF in open-access papers (continued):
Sharing a sentence is not in itself a finding about the gene and the disease.
asthma (continued). "Although the mechanism(s) of up-regulation of RhoA in OA-challenged BSMs is not known here, inflammatory cytokines such as tumor necrosis factor-α, which is also demonstrated in airways of this murine model of asthma (unpublished data), may be involved in." (PMID 15638941, 2005). "Moreover, TNF-α targeted treatment does not always prove to be effective for every asthma patient." (PMID 39407835, 2024). "We tested this hypothesis by comparing plasma cytokines, including IL-2, IL-5, IL-10, IL-13, IL-17A, IL-22, IL-33, IFN-γ, and TNF-α and the adipokine, leptin in normal weight and overweight/obese children, both with and without asthma in a cross-sectional study." (PMID 39902293, 2024). "Although a number of proinflammatory mediators may contribute to asthma per se, and may even be derived from fibroblasts, in pilot studies using a multiplex assay, we found IL-6, IL-8, CCL5 and TSLP to be particularly expressed, and importantly changed by TNFα treatment." (PMID 36760534, 2023). "Dex could not suppress the levels of TNF-α in steroid-resistant asthma mouse models." (PMID 37208441, 2023). "Although ASM are likely not a primary antigen presentation cell in asthma, their increased expression of adhesion molecules and antigen presentation gene in response to TNFα and IFNγ highlight that ASM-T cell interactions may be important and warrant further investigation." (PMID 35578269, 2022). "However, in a subsequent larger study in uncontrolled severe asthma, the anti-TNF-α antibody had no overall beneficial effects and increased the risk of serious side effects, although a post-hoc analysis suggested that patients with substantial bronchodilator reversibility had fewer exacerbations." (PMID 28114934, 2017). "Indeed, anti-TNF-α therapy has been reported to reduce the expression of MMP-9 as well as that of other inflammatory cytokines (e.g., IL-4, IL-13, and IgE), thereby hindering the recruitment of inflammatory cells and inhibiting the airway inflammation in asthma." (PMID 26783416, 2016). "Thus, consistency between mRNA and protein secretion levels is high for TNFα-induced changes, and present to varying degrees among the four cytokines for changes between fatal asthma- and non-asthma-derived ASM, with CXCL12 and IL8 showing the greatest consistency and CCL13 the weakest." (PMID 26207385, 2015). "Also the work of Beukelman and colleagues showed that JIA children had an increased rate of incident malignancy compared to children with asthma and attention deficit hyperactivity disorders, but the authors showed that specific therapies as methotrexate and TNF inhibitors did not alter this rate." (PMID 23133455, 2012). "COVID-19, Coronavírus Disease 2019; ACO, Asthma-COPD overlap; IgE, Immunoglobulin E; TNF-α, Tumor Necrosis Factor-alpha; IL, Interleukin; NOS, Non-Obstructed Smoker; SF-36, Short Form 36 Health Survey." (PMID 40997602, 2025). "In our study, an increase in OS, MDA and TNF-α levels and a decrease TAC level in children with pneumonia with and without asthma than healthy children were observed." (PMID 36076196, 2022). "Thus, TNF neutralization may have a marked potential to improve lung functions, but demonstrates serious side effects, while blocking of IL-6 does not provide significant therapeutic effect in severe asthma." (PMID 34084159, 2021). "In asthmatic children without RV infection, the concentrations of non-Th2 cytokines (IL-2, IL-8, TNF-α, and IFN-γ) were not significantly different between mild, moderate, or severe asthma measured by Pediatric Asthma Score (PAS)." (PMID 30210646, 2018). "Further, the amount of TNFα-induced cytokine inhibition by vitamin D differed among cytokines, with IL8 levels being inhibited the least in fatal asthma- and non-asthma-derived ASM cells." (PMID 26207385, 2015).
asthma (continued). "Fatal asthma-derived ASM secreted greater TNFα-induced IL8 and lower TNFα-induced CXCL12 as compared to non-asthma-derived ASM, while TNFα-induced CCL2, and CCL13 levels between fatal asthma- and non-asthma-derived ASM were not significantly different." (PMID 26207385, 2015). "Because IL8 was secreted at high levels that were significantly different between fatal asthma and non-asthma-derived ASM, we tested the dose-dependent effect of vitamin D on its TNFα-induced secretion." (PMID 26207385, 2015). "We found that TNFα treatment induced CCL2, CCL13, and IL8 mRNA expression in most fatal asthma- and non-asthma-derived ASM samples, but TNFα treatment did not induce CXCL12." (PMID 26207385, 2015). "TNF-α- or IL-1β-induced CXCL10 release by ASMC from people with and without asthma was strongly inhibited by GC and LABA treatment in this study." (PMID 23034049, 2012). "Indeed, patients with chronic cough and post-nasal drip showed increased levels of sputum neutrophils and TNF-α than normal subjects, which is line with the present findings of significant increase in sputum neutrophils in CRS patients without asthma." (PMID 32015784, 2020). "ASM cells obtained from subjects who died from an episode of asthma or subjects with a history of stable asthma show significantly enhanced expression of CD38 (both transcript and protein) to low concentrations of TNF-α compared to expression in cells from nonasthmatics." (PMID 29576747, 2018). "We observed comparatively similar levels of acute inflammatory markers (e.g., – IL-1β, IL-6, TNFα) in TRPM-stimulated whole blood from children with and without asthma, which was contrary to our a priori study hypothesis." (PMID 28424616, 2017). "While modest evidence of correlation exists for cytokines such at TNF-α, IL-1β, and IL-6, there is a notable lack of correlation evident for the IL-8 responses to endotoxin and TRPM, whether the study subjects were considered as a single group, or as sub-groups based on asthma control status." (PMID 28424616, 2017).
melanoma (876 papers, 1990 to 2026). A malignant, usually aggressive tumor composed of atypical, neoplastic melanocytes. "It is also a fact that another specific IBD therapy, anti-TNF antibodies, can increase the risk of skin cancer, such as melanoma." (PMID 40564114, 2025). "The findings indicated that biologic therapy, including TNFα inhibitors and natalizumab, was significantly associated with an increased risk of melanoma in the IBD population (OR: 1.88; 95% CI: 1.08–3.29)." (PMID 40427207, 2025). "In melanoma, 3-month TNF-α was inversely associated with survival (ρ = −0.82, 95% CI −0.97 to −0.15, p = 0.023) and response (ρ = −0.90, 95% CI −0.99 to −0.39, p = 0.006)." (PMID 41020868, 2025). "In a large nested case–control study, TNF-α antagonists were modestly associated with melanoma risk (OR 1.9; 95% CI 1.1–3.3), although Danish cohort data did not confirm this association." (PMID 41228267, 2025). "In D14 & D28 biopsy samples, genes associated with ‘TNF proteins’ feature set showed highest discrimination on the baseline of pretreatment melanoma samples." (PMID 40386779, 2025). "Studies consistently indicate that while TNFα inhibitors are associated with an increased risk of melanoma (OR: 1.88; 95% CI: 1.08–3.29), the risk is manageable with appropriate monitoring." (PMID 40427207, 2025). "TNF-induced melanoma cell dedifferentiation was also associated with the production of monohexosylceramides and dihexosylceramides." (PMID 39136013, 2024). "Among the ceramide metabolism genes being significantly downregulated in melanoma cell lines upon TNF treatment, we identified ASAH1, the gene encoding AC, the ultimate enzyme of sphingolipid lysosomal catabolism." (PMID 39136013, 2024). "Global transcriptomic analysis by RNA sequencing (RNA-Seq) demonstrated that TNF increased the expression of genes belonging to “Hallmark TNF signaling via NFKB” in TNF-treated WM35 melanoma cells." (PMID 39136013, 2024). "In conclusion, our study showed that TNF‐α released by melanoma cells caused molecular biological changes in the ANH of MLiM." (PMID 39496484, 2024). "Herein, we demonstrate that TNF-induced melanoma cell dedifferentiation is associated with a global modulation of sphingolipid metabolism." (PMID 39136013, 2024). "Collectively, these data indicate that TNF-induced melanoma cell dedifferentiation is associated with the accumulation of ceramide metabolites, which likely contribute to melanoma cell dedifferentiation." (PMID 39136013, 2024). "Concerning the risk of skin cancer, anti-TNF therapy has a potentially increased risk of developing melanoma." (PMID 36983432, 2023). "Thiopurines use in IBD has been associated with a higher risk of skin cancers, particularly non melanoma skin cancers and lymphoma, further increased by combined TNFα-antagonists." (PMID 37113615, 2023). "In a study on a huge Sweden cohort describing a small absolute risk of melanoma, patients under anti-TNFα had an increased relative risk of melanoma of 50% compared to patients without anti-TNFα." (PMID 36672491, 2023). "We further show that TNF is sufficient to induce apoptosis in Rnf31 deficient pancreatic cancer cells, in contrast to B16 melanoma cells where IFNɣ is required for TNF-induced apoptosis after Rnf31 disruption." (PMID 35379808, 2022). "This increased accumulation was associated with a reduced growth rate of B16BL6 melanoma tumors in C57BL/6 mice receiving PLD in combination with TNF-α." (PMID 36297598, 2022). "We also show that melanoma-associated PP6 inactivating mutants offer resistance to cell death due to the loss of sensitivity to TNFα." (PMID 36071040, 2022). "We followed up on this observation and report here that overexpression of Usp27x in human melanoma cells leads to loss of the cFLIPL protein and sensitizes to TNF and pIC induced apoptosis through enhanced processing of caspase-8." (PMID 35044632, 2022).
melanoma (continued). "Acute MITF loss can sensitize cells to tumor necrosis factor α (TNFα), a key inflammatory signal that is implicated in melanoma de differentiation and resistance to adoptive T‐cell therapy." (PMID 35771179, 2022). "We further show that PP6 deficient tumor cells and cells expressing melanoma-associated PP6 mutants are less sensitive to TNFα treatment." (PMID 36071040, 2022). "For example, TNF-α therapy can be used to target tumor vasculature, ensuring the melanoma cells are more susceptible to anti-tumor anti-PD-1 therapy." (PMID 34531874, 2021). "A low level of TNF-α in mice melanoma cells caused higher cancer progression by decreased necrosis, increased proliferation rate, and local microvascular density as opposed to enhanced amounts of the cytokine." (PMID 34068679, 2021). "To search for mechanisms underlying the CCL20/TNF/VEGFA secretory TAM phenotype associated with aggressive primary melanomas, and due to limited access to patient TAMs, we prepared tumor-conditioned macrophages." (PMID 34439098, 2021). "In melanoma cells, TNFα causes dedifferentiation, leading to limited recognition by T cells specific for melanocytic antigens." (PMID 32978520, 2020). "A subset of cMet+ CD8+ T cells have been identified in murine tumor models and melanoma patients, where cMet expression is associated with increased cytolytic capacity and effector functions including IFNγ/TNFα and granzyme B/perforin production." (PMID 32545260, 2020). "CCL2 macrophage recruitment into melanoma was associated with higher-grade melanoma and promotion of tumor growth through increased TNF-α dependent vascularization." (PMID 30899263, 2019). "The stimulatory effect of 1,2-DHX on TNF-α production predicts a favorable outcome in melanoma treatment, since several reports have associated the use of TNF inhibitors with an increased risk of developing skin cancer, including melanoma." (PMID 31167479, 2019). "In accordance with these data, EMSA results indicated that FKBP51 knockdown caused a decrease of nucleic NF-κB complexes in melanoma cells stimulated by irradiation or TNF-α (tumor necrosis factor α)." (PMID 30669684, 2019). "We also found that loss of JAK1 in melanoma decreased the cytotoxicity of effector T-cells and expression of associated molecules such as TNF-α, granzyme, and perforin." (PMID 30837996, 2019). "In conclusion, our study suggested that expression of TRIM59 in macrophages potentially restricts melanoma progression and metastasis, and its loss has pro-tumoral effects via induction of TNF-α." (PMID 31600735, 2019). "Melanoma growth was associated with a significant reduction in TNF-α, TLR-2 and TLR-4 mRNA expression in peritoneal macrophages compared to that in control mice (P < 0.05)." (PMID 29588627, 2018). "It is noteworthy that one of the side effects of long-term therapies with anti-TNF drugs is an increase of cancer risk, including melanoma, or demyelination." (PMID 30591049, 2018). "CRISPR/Cas9 system was utilized to edit out TNFR1 and TNFR2 on a melanoma cell line, and these knockout variants were used to test the intrinsic roles of these receptors in TNF-induced resistance to MAPKi." (PMID 30400822, 2018). "For example, there are two case-control studies of the association between TNF-α rs1800629 and melanoma risk." (PMID 28881857, 2017). "We investigated the impact of TNF deficiency on the therapeutic effect of anti-PD-1 on melanoma development." (PMID 29273790, 2017). "Anti-PD-1 treatment is associated with increased TNF gene expression in melanoma samples from metastatic melanoma patients." (PMID 29273790, 2017). "Macrophage-derived TNF-α signaling has previously been implicated in promoting radio-resistance in in vivo models of melanoma." (PMID 26799286, 2016). "Specifically, low A-SMase in melanoma accounts for the high expression of factors involved in inflammation (i.e., IL-1β, IL-6, GM-CSF, and TNF-α), which have been positively associated with cancer onset and progression." (PMID 26101462, 2015).
melanoma (continued). "We confirmed this heterogeneity by immunoblotting in time-course experiments showing that MITF loss and c-Jun accumulation after TNF-α treatment are tightly coordinated events in melanoma cells." (PMID 26530832, 2015). "Although IFN-α and IFN-β alone did not inhibit steady state IL-8 production in three metastatic melanoma variants, they did inhibit IL-1β or TNF-α-mediated upregulation of IL-8 mRNA, with a more potent effect by IFN-β compared to IFN-α." (PMID 24516470, 2014). "Reducing local expression of TNF-α was found to be associated with B16-F10 melanoma outgrowth in mice while s.c. administrating TNF-α significantly suppressed primary tumor growth of melanoma." (PMID 22304896, 2012). "The TNF-alpha pathway is perturbed in association with CNS, melanoma, and bladder tumors, among others." (PMID 22536907, 2012). "Ivanov and Ronai found that TNF-α promoted cell survival of LU125 melanoma cells as ATF 2-mediated suppression of TNF-α expression led to UVC-induced (0.06 kJ/m2) susceptibility to apoptosis." (PMID 21961050, 2011). "In vivo, BCNU and TNF, when given separately, caused tumour growth delay of B16 melanoma and of human melanoma xenografts in immune-deprived mice." (PMID 2245169, 1990). "While there are also known long-term safety risk for sustained anti-TNF therapy, which moderately increases risk of melanoma in IBD patients, these need to be balanced against the unknown long-term risk of newer drug classes." (PMID 41140764, 2026). "Apart from TNFα inhibitors, which may increase the risk of melanoma, other advanced therapies currently appear to have a reassuring safety profile regarding skin cancer development." (PMID 40427207, 2025). "A therapy with biologics (TNF-inhibitors) can increase the risk of melanoma." (PMID 40564114, 2025). "Alternative treatments to anti-TNF agents and calcineurin inhibitors may be preferable in melanoma survivors or high-risk patients." (PMID 41228267, 2025). "Limited studies suggest that patients treated with methotrexate or tumor necrosis factor-alpha inhibitors may have a slightly increased risk of melanoma." (PMID 41158454, 2025). "Furthermore, dedifferentiation can render melanoma cells hypersensitive to the inflammatory cytokine TNFα, causing increased expression of immunomodulatory cytokines." (PMID 39736644, 2024). "A study showed that TNF expression is positively associated with expression of PD-L1 in human melanoma specimens indicating that TNF blockade could potentially prevent PD-L1 expression." (PMID 39311981, 2024). "The most consistent evidence for increased cancer risk among people with IBD exists for those treated with thiopurine medications (at risk for lymphoma, and non-melanoma skin cancer), and among those treated with anti-tumor necrosis factor (anti-TNF) biological therapy (at risk for melanoma)." (PMID 38592255, 2024). "We analyzed 187 consecutive patients who were treated with ILP (melphalan or melphalan associated with TNF-alpha) for advanced melanoma at the Veneto Institute of Oncology of Padua (Italy) and the Padua University Hospital (Italy) between June 1989 and September 2021." (PMID 38793023, 2024). "Moreover, TNFα from THP1 macrophages induced expression of the transcription factor MITF in melanoma cells, which was associated with a decrease in BRAFi/MEKi-induced cell death." (PMID 38942020, 2024). "However, several studies have demonstrated a slightly higher risk of melanoma in association with anti-TNF biologic therapy." (PMID 37674502, 2023). "Whereas anti-TNF monotherapy potentially increased the risk of lymphoma and melanoma." (PMID 36983432, 2023). "IBD patients undergoing anti-TNF therapy are reportedly at higher risk for melanoma." (PMID 36831424, 2023). "Indeed, thiopurine use is associated with an increased risk for non-melanoma skin cancer (NMSC) and lymphoma, and anti-TNF use is associated with a higher risk for melanoma and lymphoma." (PMID 36831424, 2023).